TREX2 (three prime repair exonuclease 2)
Description:
Exonuclease with a preference for double-stranded DNA with mismatched 3' termini. May play a role in DNA repair.
Tractability: Small molecule: it has a binding pocket of medium quality. PROTAC: ubiquitination databases record sites on it.
Gene: Protein-coding gene on chromosome X (153,444,473 to 153,470,587, reverse strand). Ensembl gene ENSG00000183479.
Subcellular location: Nucleus
Gene Ontology:
Molecular function: 3'-5'-DNA exonuclease activity; DNA binding; magnesium ion binding; molecular adaptor activity; protein binding; protein homodimerization activity; 3'-5' exonuclease activity; double-stranded DNA 3'-5' DNA exonuclease activity; nucleic acid binding
Biological process: DNA metabolic process; DNA repair
Cellular component: nucleus
Homologues: Orthologues: mouse Trex2 (88% identical), guinea pig TREX2 (87% identical), rat Trex2 (87% identical), rabbit TREX2 (80% identical), tropical clawed frog trex2 (47% identical), Drosophila melanogaster CG3165 (34% identical), zebrafish plex9.2 (24% identical), zebrafish plex9.1 (23% identical), Caenorhabditis elegans W02F12.4 (22% identical). Paralogues in human: TREX1 (46% identical).
Diseases named in the same sentence as TREX2 in open-access papers:
TREX2 is named in the same sentence as 24 diseases in open-access papers, as found by Europe PMC text mining. Sharing a sentence is not in itself a finding about the gene and the disease. The quoted sentences say what the papers report.
colorectal cancer (4 papers, 2015 to 2024). A primary or metastatic malignant neoplasm that affects the colon or rectum. "We investigated the intragenic methylation loss at the three prime repair exonuclease 2 (TREX2) locus in laryngeal (n = 256) and colorectal cancer cases (n = 95) and in pan-cancer data from The Cancer Genome Atlas (TCGA)." (PMID 31053176, 2019). "In this context, a germline TREX2 inactivating mutation has been reported in one colorectal cancer patient." (PMID 26090614, 2015). "TREX2 was depleted with short hairpin RNA (shRNA) in HCT116 cells derived from colorectal carcinoma, SK-OV-3 cells derived from ovarian adenocarcinoma, and CCRF-CEM cells derived from lymphoblastic leukemia." (PMID 38175749, 2024). "Among the identified genes, SP5, SIX4, TREX2, and SPP1 were upregulated and were adverse prognostic factors in colorectal cancer." (PMID 39309424, 2024).
laryngeal carcinoma (3 papers, 2019 to 2022). Carcinoma that arises from the laryngeal epithelium. "Another study reported that methylation loss at the three-prime repair exonuclease 2 (TREX2) locus was observed in laryngeal cancer, and that low TREX2 DNA methylation was associated with elevated TREX2 expression and prolonged OS in laryngeal cancer." (PMID 36338767, 2022). "Based on the functional link of DNA methylation and gene expression, we investigated the possible association of TREX2 DMR methylation with overall survival in our laryngeal cancer cohort." (PMID 31053176, 2019). "Methylation loss correlated with immunohistochemically staining for TREX2 (p < 0.0001) in laryngeal tumors and improved overall survival of laryngeal cancer patients (p = 0.045)." (PMID 31053176, 2019). "We suggest that the association which we see between methylation loss and increased TREX2 expression could be responsible for beneficial downstream events like improved immune response and the survival benefit observed in a subgroup of laryngeal cancer patients." (PMID 31053176, 2019). "TREX2 is a gene recently reported to be involved in mutagen-induced skin and oral carcinogenesis and DNA repair and might thus also be linked to the etiology of laryngeal cancer." (PMID 31053176, 2019). "Using immunohistochemistry (IHC), we measured TREX2 protein levels in laryngeal cancer and adjacent normal tissue samples representative for high and low TREX2 DNA methylation." (PMID 31053176, 2019). "TREX2 DMR methylation was associated with altered protein and mRNA expression and improved survival in patients with laryngeal cancer from Germany and TCGA, suggesting a role of TREX2 methylation in cancer etiology." (PMID 31053176, 2019). "Finally, when we correlated TREX2 mRNA expression with the overall survival in the TCGA cancer studies, significant HRs were calculated for laryngeal cancer (HR = 0.726; CL = 0.589–0.895, p = 0.0027) and CRC patients." (PMID 31053176, 2019). "The data highlight a regulatory role of TREX2 DNA methylation for gene expression which might affect incidence and survival of laryngeal cancer." (PMID 31053176, 2019). "We here quantified DNA methylation at the DNA repair gene three prime repair exonuclease 2 (TREX2) in tumor tissue compared to adjacent normal tissue in an independent, population-based case-control study of laryngeal cancer patients from Germany." (PMID 31053176, 2019). "DNA methylation of the TREX2 gene was measured in formalin-fixed paraffin-embedded (FFPE) tumor (n = 181) and adjacent non-tumor tissue samples (n = 75) from the German laryngeal cancer study." (PMID 31053176, 2019).
psoriasis (3 papers, 2017 to 2024). An autoimmune condition characterized by red, well-delineated plaques with silvery scales that are usually on the extensor surfaces and scalp. "The abnormal expression level of TREX2 can result in broken chromosome, increased susceptibility to skin carcinogenesis and Psoriasis." (PMID 30357414, 2018). "Moreover, TREX2 has been demonstrated as a key player in contributing to the pathogenesis of psoriasis by promoting DNA degradation during keratinocyte death." (PMID 30357414, 2018). "Therefore, TREX2 has been recognized as a promising therapeutic target for the treatment of psoriasis." (PMID 30357414, 2018). "Deletion of Trex2 also enhanced parakeratosis in the imiquimod-induced model of psoriasis in mice." (PMID 28928425, 2017).
prostate carcinoma (2 papers, 2015 to 2020). A carcinoma that arises from epithelial cells of the prostate gland. "Interestingly, the TREX2 R156L variant, which results in a significant loss of function, presents also a slightly higher frequency in sporadic prostate cancers." (PMID 26090614, 2015).
actinic keratosis (1 paper, 2015). A precancerous lesion of the skin composed of atypical keratinocytes. "The analysis of TREX2 by immunofluorescence in human precancerous actinic keratosis lesions and keratinocyte-derived tumors, including cSCCs and HNSCCs, revealed a frequent deregulated expression of this exonuclease in squamous carcinogenesis." (PMID 26090614, 2015). "Interestingly, in actinic keratosis lesions, TREX2 expression increased in upper keratinocyte layers and displayed predominantly nuclear localization." (PMID 26090614, 2015).
colon cancer (1 paper, 2019). "In summary, survival benefits in laryngeal and colon cancer patients linked to TREX2 DMR methylation loss imply a functional role of this region in tumorigenesis." (PMID 31053176, 2019).
gastric cancer (1 paper, 2026). A primary or metastatic malignant neoplasm involving the stomach. "Additionally, SUMO-2/3 has been shown to stabilize NSUN2 and facilitate its nuclear transport in gastric cancer 48, while glucose-induced oligomerization and activation of NSUN2 promote TREX2 expression, suppressing cGAS/STING activation to regulate oncogenic activity in cancer cells." (PMID 41356184, 2026).
head and neck cancer (1 paper, 2019). A primary or metastatic malignant neoplasm affecting the head and neck. "Interestingly, this improved survival is not found when analyzing all TCGA HNSC cases, indicating that TREX2 may have specific functions or regulation in laryngeal tissue distinct from other common sites of head and neck cancer." (PMID 31053176, 2019).
inflammatory skin disease (1 paper, 2015). Inflammatory skin disorders covers a broad category that includes many conditions ranging in severity, from mild itching to grave medical health complications These disorders are common in people of all ages and races. "Further insight into the mechanisms by which TREX2 regulates skin immunity under stress conditions may have major implications in the understanding of inflammatory skin diseases." (PMID 26090614, 2015).
skin tumors (1 paper, 2015). "To determine the relevance of TREX2 in UVB-induced skin carcinogenesis, we compared the susceptibility of wt and Trex2−/− mice to the development of skin tumors." (PMID 26090614, 2015).
squamous cell carcinoma (1 paper, 2015). A carcinoma arising from squamous epithelial cells. "TREX2 expression was up-regulated by chronic UV exposure whereas it was de-regulated or lost in human squamous cell carcinomas (SCCs)." (PMID 26090614, 2015).
tumor (9 papers, 2015 to 2025). "Nevertheless, Trex2 knockout mice show increased susceptibility to DNA damage-induced skin tumorigenesis." (PMID 35883600, 2022). "TREX2 deficiency increases skin carcinogenesis induced by chemical or UVB radiation." (PMID 26090614, 2015). "TREX2 deregulation and genetic alterations in cancer mostly indicate the role of TREX2 as a tumour suppressor." (PMID 35883600, 2022). "Our data support literature data on the role of TREX2 in carcinogenesis as tumor patients with high TREX2 expression show improved overall survival in our analysis." (PMID 31053176, 2019). "Dysfunctional TREX2 leads to reduced cell proliferation and increased susceptibility to drug- or UV-induced skin carcinogenesis, highlighting the important role of TREX2 in DNA replication and tumor suppression." (PMID 30357414, 2018). "Similar to NM23-H1, a tumor suppressor that also possess 3′-5′ exonuclease activity, TREX2 is highly expressed in premalignant lesions, but is lost with tumor dedifferentiation." (PMID 26090614, 2015). "We next compared genetic variability of the exonuclease TREX2 by sequencing the human TREX2 gene in tumor and blood samples obtained from HNSCC patients and healthy controls." (PMID 26090614, 2015). "Trex2−/− mice developed tumors earlier, and tumor incidence was significantly greater in the Trex2−/− mice relative to their wt counterparts (P = 0.025, Log-rank Mantel-Cox Test)." (PMID 26090614, 2015). "In support of a relevant tumor suppressor role for TREX2 in squamous tumorigenesis, we observed alterations in the TREX2 gene and TREX2 expression in human SCCs." (PMID 26090614, 2015). "Moreover, NSUN2 functions as a glucose sensor, ensuring mRNA stability of three prime repair exonuclease 2 during glucose deficiency, thereby inhibiting the GAS/STING pathway, sustaining tumor development, and conferring resistance to immune therapy." (PMID 39164641, 2024). "Studies on the role of TREX2 as a tumour suppressor have reported contrasting results." (PMID 35883600, 2022). "In artificial settings, chromosomal and genomic instability were reported using Trex2-null and mutated embryonic stem cells; however, TREX2 deficiency in mice does not lead to a tumour prone phenotype." (PMID 35883600, 2022). "Triple repair nucleic acid exonuclease 2 (TREX2) has a DNA repair function and may exert a tumour suppressive effect." (PMID 36443876, 2022). "We hypothesize that this seemingly contradictory finding highlights TREX2 as part of a tumor suppressive transcriptional response possibly triggered by oncogenesis and consequential replication stress and DNA damage." (PMID 31053176, 2019). "Moreover, we observed a weak trend for an increase of TREX2 mRNA expression in tumor samples compared to controls in several TCGA datasets." (PMID 31053176, 2019). "Therefore, TREX2 deficiency was associated with increased UVB-induced skin tumorigenesis, supporting a tumor suppressor role for this exonuclease in the skin upon DNA damage." (PMID 26090614, 2015). "Thus, TREX2 staining exhibited a heterogeneous pattern throughout the tumor, but was relatively intense in differentiated areas of mainly non-metastatic and well-differentiated tumors." (PMID 26090614, 2015). "Furthermore, TREX2 levels and patterns of expression in cSCCs varied depending on the degree of tumor differentiation and metastasis." (PMID 26090614, 2015). "In addition, strong TREX2 staining was also detected in tumor-associated stroma for a significant subset of non-metastatic cSCCs." (PMID 26090614, 2015). "By sustaining TREX2 expression, NSUN2 limits cytosolic dsDNA accumulation and suppresses cGAS/STING-mediated innate immune responses, thereby facilitating tumor progression and resistance to anti-PD-L1 therapy." (PMID 41256859, 2025). "Among these genes, PLK1, CDC25C, ESCO2, AXIN2, TREX2, ALKBH2, and MC1R were upregulated in tumor tissues, whereas IGF1 and ESR1 presented downregulation." (PMID 35484177, 2022).
tumor (continued). "Rare genetic inactivation of TREX2 has been reported in CRC, suggesting that TREX2 has a tumor suppressive function." (PMID 31053176, 2019).
cancer (8 papers, 2015 to 2026). A tumor composed of atypical neoplastic, often pleomorphic cells that invade other tissues. "In cancers, recent data have indicated heterogeneous TREX2 levels caused by aberrant regulation." (PMID 31053176, 2019). "Other TREX-2 components like ENY-2, which is associated with deubiquitination machinery, are also markedly elevated in many types of cancers including hepatocellular carcinoma and ovarian cancer." (PMID 39769375, 2024). "In this review, we focus on the relationship between deregulated mRNA export through the transcription-export-2 (TREX-2) complex and cancer development." (PMID 39769375, 2024). "The defective function of the TREX-2 complex has been shown to augment the sensitivity of cancer cells towards chemotherapy." (PMID 39769375, 2024). "Comparison of RNA expression data from further TCGA studies revealed higher expression of TREX2 in seven cancer studies which showed also lower DNA methylation." (PMID 31053176, 2019). "In fact, the relatively weak correlation of TREX2 mRNA expression and methylation in some cancers points to additional layers of regulation on the posttranscriptional level." (PMID 31053176, 2019). "The described contribution of TREX2 protein to DNA double-strand break repair might highlight this protein as an interesting target for potential cancer therapies." (PMID 31053176, 2019). "Our work provides a basis for the understanding of differential TREX2 regulation in cancer." (PMID 31053176, 2019). "In addition, we investigated TREX2 DNA methylation in several TCGA cancer studies." (PMID 31053176, 2019). "To further investigate a functional link between TREX2 methylation and expression, we screened eight cancer cell lines of different tissue origin and three normal human epidermal keratinocytes (NHEK) for a correlation between TREX2 mRNA levels and methylation." (PMID 31053176, 2019).
infection (1 paper, 2014). The state of being infected such as from the introduction of a foreign agent such as serum, vaccine, antigenic substance or organism. "Primary MEFs derived from XID embryos were co-transduced by LVs expressing the 6RVD-TALE-XID and TREX2 (multiplicity of infection (MOI) of 10)." (PMID 24682825, 2014).
TREX2 also shares sentences with these, for which no sentence is quoted: autoimmune disease (1 paper); bladder cancer (1); COVID-19 (1); head and neck squamous cell carcinoma (1); laryngeal tumors (1); lymphoblastic leukemia (1); melanoma (1); ovarian adenocarcinoma (1); systemic lupus erythematosus (1); virus infection (1).